LINC01210 (long independently transcribed non-coding RNA 1210)
Gene: Long non-coding RNA gene on chromosome 3 (137,771,178 to 137,780,882, forward strand). Ensembl gene ENSG00000239513.
Diseases named in the same sentence as LINC01210 in open-access papers:
LINC01210 is named in the same sentence as 1 disease in open-access papers, as found by Europe PMC text mining. Sharing a sentence is not in itself a finding about the gene and the disease.
LINC01210 shares sentences with these, for which no sentence is quoted: Alzheimer disease (1 paper).